SPARCL1 (SPARC like 1)
Diseases named in the same sentence as SPARCL1 in open-access papers (continued):
Sharing a sentence is not in itself a finding about the gene and the disease.
tumor (continued). "To further confirm the prognostic value of the hub genes with prognostic values, we used immunohistochemical (IHC) staining to detect the protein expression of CDH2 and SPARCL1 in normal tissues and tumor tissues." (PMID 34422629, 2021). "There were significant correlations between SPARCL1 down regulation, poor prognosis, survival, histological type, and tumor size." (PMID 32467737, 2020). "SPARC like protein 1 (SPARCL1) is a matricellular protein involving in tumor progression and tissue regeneration." (PMID 32467737, 2020). "Overall, human SPARCL1 can be considered a vascular-derived and therefore angiocrine tumor suppressor." (PMID 32437418, 2020). "The prognostic value of SPARCL1 and tumour architecture is independent in multivariate analysis, compared to other currently known prognostic factors." (PMID 30987093, 2019). "Our data showed that the expression level of SPARCL1 was downregulated in M1 tumours compared with M0 tumours." (PMID 30987093, 2019). "Both SPARCL1 presentation and tumour architecture were significant in regard to systemic UTUC recurrence in our institutional cohort." (PMID 30987093, 2019). "The migration of BFTC909 cells was significantly enhanced by SPARCL1 knockdown, while overexpression of SPARCL1 inhibited cell migration, indicating that the tumour behaviour of BFTC909 cells was less aggressive after SPARCL1 overexpression." (PMID 30987093, 2019). "In vitro UTUC behaviour revealed that the UTUC cell line (BFTC909) weakly expressed SPARCL1, which is compatible with its aggressive tumour behaviour." (PMID 30987093, 2019). "The expression of SPARCL1 in pathologic tumor stages 3 and 4, patients were significantly lower than that in pathologic tumor stages 0, 1, and 2, patients on the basis of a comparison of immunoreactivity score." (PMID 30987093, 2019). "In the present study, an analysis of the clinicopathological features showed that low expression ratio of SPARCL1 markedly increased tumor size, mitotic index (/50HPF), and number of distant metastasis at the time of initial diagnosis and tumor progression." (PMID 29973149, 2018). "Specifically, there was significantly correlation between SPARCL1 expression and tumor size, mitotic index (/50HPF), distant metastasis at the time of initial diagnosis (P < 0.05)." (PMID 29973149, 2018). "Down-regulated genes in E2-treated CD133+/CD34+ cells also included the newly characterized tumor suppressor genes DOCK4, a member of the CDM gene family, and SPARCL1, which encodes an extracellular matrix-associated glycoprotein." (PMID 17559657, 2007). "To validate differential expression of two candidate markers at the protein level, we performed immunohistochemistry to detect CD24 antigen and SPARCL-1 protein in a pair of slides representing a benign and malignant tumour." (PMID 16969345, 2006). "With respect to SPARCL1, strong staining was observed in both tumour cells and stroma of the endometrioid adenomyofibroma." (PMID 16969345, 2006). "The tumor-suppressive outcome is driven by combined molecular changes: downregulation of SPARCL1 and PSME3, coupled with upregulation of the NF-κB inhibitor NFKBIA and downregulation of CD44 and CCL15, collectively promotes apoptosis while suppressing proliferation, migration, and angiogenesis." (PMID 41465234, 2025). "Furthermore, higher expressed SPARCL1 was related to an increased likelihood of higher T stage, suggesting its involvement in tumour growth and invasion." (PMID 39548034, 2024). "Taken together, our results indicate that SPARCL1 may have important functions in modulating immune responses in tumour microenvironment." (PMID 39548034, 2024). "While some researches have confirmed a tumour‐suppressive role of SPARCL1 across various cancer types, it has also been demonstrated to promote cancer progression in specific cancers, indicating diverse functions of SPARCL1 depending on the type of cancer." (PMID 39548034, 2024).
tumor (continued). "Collectively, these findings provide further evidence suggesting that SPARCL1 might function during recruitment of immune cells within tumour microenvironment." (PMID 39548034, 2024). "Furthermore, downregulation of SPARCL1 expression enhances liver metastasis of malignant gastrointestinal stromal tumor cells." (PMID 37180578, 2023). "Furthermore, different survival analyses for the SPARCL1 gene demonstrated distinct conclusions for the same tumor." (PMID 36483097, 2022). "Finally, the correlations between SPARCL1 and tumor microenvironment scores, tumor-infiltrating immune cells in CRC were determined by “ESTIMATE” and “GSVA” R packages." (PMID 35111844, 2022). "Furthermore, SPARCL1 negatively regulated tumor cell migration and invasiveness in vitro and tumor metastatic growth in vivo." (PMID 35111844, 2022). "SPARCL1 is a secreted protein and plays a tumor suppressor role in several tumors." (PMID 35971182, 2022). "Our studies demonstrated that SPARCL1 significantly correlated with clinicopathological features, overall survival, and tumor microenvironment in CRC, which might help us better understanding the roles of SPARCL1 in CRC." (PMID 35111844, 2022). "One study showed that SPARCL1 could regulate tumor microenvironment-dependent endothelial cell heterogeneity in CRC." (PMID 35111844, 2022). "This research may be helpful to further comprehend the functions of SPARCL1 and the mechanisms between SPARCL1 and tumor microenvironment." (PMID 36483097, 2022). "One study showed that SPARCL1 could regulate tumor microenvironment-dependent endothelial cell heterogeneity in CRC, making our results more convincing." (PMID 35111844, 2022). "SPARCL1 is considered a tumor suppressor, which inhibits tumor progression in a variety of tumors." (PMID 35281077, 2022). "Our study demonstrated that SPARCL1 correlated with stromal score, immune score, and ESTIMATE score, which indicated that SPARCL1 might play important roles in tumor environment." (PMID 35111844, 2022). "Intriguingly, overexpression of SPARCL1 in HCC cells remarkably inhibited tumor growth in vivo." (PMID 36483097, 2022). "We further explored the correlations between SPARCL1 and tumor-infiltrating immune cells in CRC." (PMID 35111844, 2022). "However, previous studies suggest that several of the identified proteins are potent stimulators of tumor cell proliferation or invasiveness, including SPARCL1, IGF-BP2, osteopontin, FAM3C, TREM2, CD166, prosaposin, and kininogen-1/bradykinin." (PMID 35659255, 2022). "In addition, mouse staining was controlled with tissues derived from a Sparcl1 complete knockout mouse, and in human studies, comparisons between healthy tissue and respective tumor tissue of the same organs were used." (PMID 32437418, 2020). "Here, the functions of SPARCL1-secreting ECs in particular might be one reason for the downregulation of hSPARCL1 expression in neoplastic tissues in the course of tumor escape, which we found in accordance with previous studies." (PMID 32437418, 2020). "The negative association between the SPARCL1 expression and poor tumour differentiation indicates the major role of aggressive tumour behavior." (PMID 30987093, 2019). "SPARCL1 is expressed in many tissues and downregulated in a wide variety of human malignancies, which suggests that SPARCL1 might play a role as a tumor suppressor gene." (PMID 29973149, 2018). "In other words, the later clinical stage of tumor, the lower expressing of SPARCL1 would be." (PMID 29973149, 2018). "Factors associated with PFS by Kaplan-Meier univariate analysis were radical degree (P < 0.001), distant metastasis at the time of initial diagnosis (P < 0.05), tumor size (P < 0.001), mitotic count (P < 0.001), NIH risk classification (P < 0.001), and SPARCL1 expression (P < 0.001)." (PMID 29973149, 2018). "This suggests that SPARCL1 inactivation is a frequent event in tumours of epithelial origin." (PMID 16969345, 2006).
tumor (continued). "SPARC-like protein 1 (SPARCL1) is an extracellular matrix protein involved in regulating cell adhesion, proliferation, and migration; promoting cellular quiescence and vascular endothelial homeostasis; and exhibiting tumor-suppressive effects in certain cancers." (PMID 40649979, 2025). "However, the precise functional significance of SPARCL1 and its interactions with the tumour microenvironment remain unclear." (PMID 39548034, 2024). "Besides, SPARCL1 is correlated with tumor environment in CRC." (PMID 35111844, 2022). "Moreover, as a plasma protein, SPARCL1 may promote tumor cell metastasis by promoting the secretion of granules (endocytosis and exocytosis)." (PMID 34422629, 2021). "Multivariate Cox regression analysis revealed that only negative SPARCL1 expression and nonpapillary tumour architecture were independently associated with systemic recurrence compared with currently known prognostic factors (p = 0.011 and 0.008, hazard ratios = 2.89 and 3.01, respectively)." (PMID 30987093, 2019). "Above findings suggested that SPARCL1 may function as a tumor suppressor in gastric GIST." (PMID 29973149, 2018). "Furthermore we identified SPARCL1 with higher expression levels among the benign samples than the malignant ones (p = 0.01), and previous investigations discussed this protein’s possible involvement as a suppressor of a variety of tumor types." (PMID 23557354, 2013). "Mechanistically, SPARCL1 appears to mediate its anti-tumor effects through the SLC3A2-mediated ferroptosis pathway, suggesting a novel mechanism by which SPARCL1 influences PTC progression." (PMID 42160309, 2026). "Elevated promoter methylation events involved 168 genes with reduced tumor expression, and it was notable that promoter hypermethylation of AMT, CCL21 and SPARCL1 were detected in the vast majority of tumors." (PMID 39104720, 2024). "Among these five genes, the SPARCL1, EFEMP1 and MFAP4 had significant highly methylation between normal and tumor tissues using GSCA online platform." (PMID 37563710, 2023). "The highly methylated level between tumor and normal tissues were ALDH1A3, EFEMP1, SPARCL1, CPXM2 and EFEMP1." (PMID 37563710, 2023). "The mechanism of miR-539-3p-mediated tumorigenesis was targeted SPARCL1, RNF2, CTBP1, or CDK14 and inhibited the expression of these proteins in tumor cells." (PMID 35303885, 2022). "Radiation alone (0, 2, 4, 6, or 8 Gy) or in combination with SPARCL1 overexpression restrained clonogenic formation in BFTC909 and the combined treatment had a synergistic anti-tumor effect." (PMID 30987093, 2019). "In the tumor epithelium, there were only three genes (POSTN, periostin; SPARC, osteoconectin; SPARCL1, SPARC-like 1) that were significantly upregulated in IDC relative to DCIS." (PMID 19187537, 2009). "In addition, we conducted animal experiments to detect the effects of SPARCL1 on the subcutaneous tumor formation and multi-organ metastasis of PTC cells in mice, as well as the inhibitory effect of recombinant SPARCL1 on tumors formed by PTC cells." (PMID 42160309, 2026). "Nevertheless, the role of SPARCL1 across cancers has not yet been widely elucidated and few pan-cancer studies exist to suggest the relationship between SPARCL1 and various tumor types." (PMID 36483097, 2022). "The SPARCL1+ and CRHBP+ were identified for tumor and normal derivation respectively." (PMID 35017463, 2022). "In order to study the expression patterns of genes in tumors and normal cell lines, PCR was used to detect the mRNA expression of genes, and the results showed that the expression of SPARCL1, HAND1, CLEC10A, PTGS1 genes in tumor group was significantly lower than that in the normal group." (PMID 35281077, 2022). "Several proteins that are involved in tumor growth were present in glioblastoma cyst fluid (for references, see “Discussion” section): SPARCL1, IGF-BP2, osteopontin, FAM3C, TREM2, CD166, and prosaposin promote tumor cell proliferation, migration, and invasiveness." (PMID 35659255, 2022).
tumor (continued). "Furthermore, PS cells overexpressed BRCA1 and SPARCL1, already known in GBM to promote tumor cell viability, migration and invasion and to correlate with patients prognosis." (PMID 31231613, 2019). "Growing evidences show that SPARCL1 often presents a reduced or absent expression pattern in many human epithelial cancers, suggesting its role as tumor suppressor." (PMID 29973149, 2018). "Finally, tumor-relevant behaviors of ESCC cells were observed in different treatment groups, and finding that adding SC-79 promoted ESCC cell proliferation, migration, and invasion and counteracted the inhibitory effect of SPARCL1 on ESCC cells." (PMID 35309127, 2022). "SPARCL1 was significantly downregulated in the gastric GIST with high-grade malignance as compared with low-grade malignance, its expression was closely correlated with tumor size, mitotic index, distant metastasis at the time of initial diagnosis and tumor progression of GIST (P < 0.05)." (PMID 29973149, 2018).
cancer (41 papers, 2006 to 2026). A tumor composed of atypical neoplastic, often pleomorphic cells that invade other tissues. "Pan-cancer analyses reveal that SPARCL1 is associated with both pro-tumorigenic and anti-tumorigenic immune components." (PMID 40426943, 2025). "Further investigations are warranted to unravel the precise mechanisms underlying the functions of SPARCL1 and to validate its utility as a prognostic marker and therapeutic target in various cancer contexts." (PMID 39548034, 2024). "On the other hand, RNA-seq data showed that four other genes (DUSP6, NFIX, VIM, and SPARCL1) associated with cancer were also downregulated in CREB5 knockdown cells." (PMID 38418476, 2024). "As M2 macrophages demonstrated moderate and strong correlations with SPARCL1 expression across cancers, it would be interesting to study the underlying mechanism between SPARCL1 and the M2 macrophages." (PMID 36483097, 2022). "SPARCL1 codes for a secreted glycoprotein which regulates extracellular matrix (ECM) and cell-matrix adhesion SPARCL1 inhibits cell proliferation and migration and reduced SPARCL1 expression has been linked to cancer metastases." (PMID 28966918, 2017). "SPARCL1, a known tumor suppressor gene in various cancers, encodes a secreted glycoprotein." (PMID 42160309, 2026). "We demonstrated that mutation count was elevated in the altered SPARCL1 group in several cancers." (PMID 36483097, 2022). "We then evaluated the association between SPARCL1 and the pathological stages across cancer types." (PMID 36483097, 2022). "Moreover, we focused on the association between SPARCL1 transcriptional level and the immune infiltration levels across cancers." (PMID 36483097, 2022). "Studies showed that the SPARCL1 gene may be associated with the Wnt/β-catenin pathway and has a role in cancer as well as other diseases, so we tested whether the SPARCL1 gene can regulate the Wnt/β-catenin pathway affecting preadipocyte differentiation." (PMID 34872433, 2021). "Secreted protein acidic and rich in cysteine-like 1 (SPARCL1) is a matricellular glycoprotein expressed by astrocytes and stromal cells, whose expression varies across cancer types." (PMID 42123596, 2026). "SPARCL1 has been widely studied in the context of cancer progression, and knockout of the Sparcl1 gene in mice has been shown to significantly increase vascular permeability." (PMID 40649979, 2025). "SPARCL1, a secreted glycoprotein, has been frequently found to be inhibited in various cancer types." (PMID 39548034, 2024). "Analysis of transcriptional features of SPARCL1 across various cancers was conducted using the TIMER2.0 website." (PMID 39548034, 2024). "With the research on SPARCL1 going deeper in recent years, it has been found to play a vital role in affecting progression of cancers through being regulated by miRNAs." (PMID 35309127, 2022). "A qRT-PCR result showed that SPARCL1 was poorly expressed in ESCC cancer tissue and cells, and the expression trend of miRNA-105-5p was opposite." (PMID 35309127, 2022). "Another major finding was the correlation of SPARCL1 and diverse immune infiltration levels across cancers." (PMID 36483097, 2022). "Especially, immune marker sets of M2 macrophages demonstrated moderate or strong correlations with SPARCL1 across cancers." (PMID 36483097, 2022). "As previous results demonstrated that SPARCL1 was down-regulated in several human tumors, we identified the expression of SPARCL1 in TCGA across cancers." (PMID 36483097, 2022). "Remarkably, we revealed that SPARCL1 expression level impacted the OS in 8 types of cancers, including BLCA, COAD, KIRP, MESO, UVM, KIRC, LGG, and LUAD." (PMID 36483097, 2022). "To evaluate the prevalence of SPARCL1 genetic alterations, we queried the pan-cancer TCGA atlas (n = 10,950)." (PMID 36483097, 2022). "In summary, we demonstrated that SPARCL1 was down-regulated in most cancer types and correlated with the pathological stages and the prognosis across cancer types." (PMID 36483097, 2022).